SNHG17 (small nucleolar RNA host gene 17)
Diseases named in the same sentence as SNHG17 in open-access papers (continued):
Sharing a sentence is not in itself a finding about the gene and the disease.
rectal cancer (3 papers, 2020 to 2024). A primary or metastatic malignant neoplasm that affects the rectum. "This work aimed to explore the roles and associated mechanisms of small nucleolar RNA host gene 17 (SNHG17) in rectal cancer." (PMID 34249085, 2021). "Collectively, we explored the roles and mechanisms of SNHG17 in rectal cancer and discovered that SNHG17 upregulated expression in rectal cancer tissues and cells." (PMID 34249085, 2021). "We found that the knockdown of SNHG17 suppresses cell proliferation by stimulating cell apoptosis, indicating the involvement of SNHG17 in regulating the malignant behaviors of rectal cancer cells." (PMID 34249085, 2021). "Functionally, knockdown the expression of SNHG17 inhibits rectal cancer cell proliferation via stimulating cell apoptosis." (PMID 34249085, 2021). "Considering that SNHG17 are overexpressed in rectal cancer, this work silenced SNHG17 expression." (PMID 34249085, 2021). "In addition, we found that increased SNHG17 expression could stimulate STC2 expression levels in rectal cancer cells (0.95 ± 0.12 vs. 4.35 ± 0.41 in SW837, 1.00 ± 0.13 vs. 5.36 ± 0.31 in SW1463, p < 0.001)." (PMID 34249085, 2021).
tongue squamous cell carcinoma (3 papers, 2020 to 2021). A squamous cell carcinoma that arises from the tongue. "For example, recent studies showed that SNHG17 promotes tumor cell proliferation and invasion in tongue squamous cell carcinoma and CRC by sponging miR-23a-3p and miR-876, respectively." (PMID 34782005, 2021).
astrocytoma (2 papers, 2020 to 2022). "The investigation on the regulatory mechanism of SNHG17 in astrocytoma begins with exploring its subcellular place." (PMID 32883232, 2020). "Data of nuclear cytoplasm fractionation and FISH assays exhibited that SNHG17 was primarily distributed in the cytoplasm, which unveiled the possibility of SNHG17 to participate in a ceRNA network in astrocytoma." (PMID 32883232, 2020). "Then EdU and CCK8 assays indicated that the proliferation of astrocytoma cells was restrained by knockdown of SNHG17." (PMID 32883232, 2020). "Taken together, miR-876-5p could bind to SNHG17 and repressed the malignant course of astrocytoma cells." (PMID 32883232, 2020). "Moreover, how SNHG17 exerted its function in astrocytoma by modulating its downstream targets was investigated in ceRNA network." (PMID 32883232, 2020). "Likewise, the migration and invasion abilities of astrocytoma cells were lessened by down-regulated SNHG17." (PMID 32883232, 2020). "In this study, we analyzed the role of SNHG17 in astrocytoma cells." (PMID 32883232, 2020). "Moreover, SNHG17 silence could repress the proliferation, migration and invasion of astrocytoma cells." (PMID 32883232, 2020).
colon adenocarcinoma (2 papers, 2021 to 2024). "LncRNA-small nucleolar RNA host gene 17 (SNHG17) was found to be elevated in colon adenocarcinoma (COAD) tissues and cells." (PMID 34494089, 2021).
diabetes (2 papers, 2020 to 2022). "However, SNHG17 was found to be negatively associated with high-density lipoprotein cholesterol (HDL-C) levels in a study on diabetes and may be involved in the formation of type 2 diabetes." (PMID 36185210, 2022).
esophageal squamous cell carcinoma (2 papers, 2021 to 2022). Esophageal squamous cell carcinoma (ESCC) is a type of esophageal carcinoma (EC) that can affect any part of the esophagus, but is usually located in the upper or middle third. "However, for esophageal squamous cell carcinoma (ESCC) the expression pattern and detailed function of SNHG17 are largely unknown." (PMID 34429400, 2021).
lung carcinoma (2 papers, 2022 to 2023). "In our finding, we confirm that hypomethylation for the promoter of MIR503HG/SNHG17 results in its overexpression in lung cancer." (PMID 35719962, 2022). "In general, our study reveals the role of LGG/SNHG17/PTBP1 in attenuating lung cancer cell proliferation and EMT progression, and suggests that SNHG17 may serve as a novel therapeutic target for RIPF." (PMID 36635762, 2023).
renal carcinoma (2 papers, 2021 to 2025). A carcinoma arising from the epithelium of the renal parenchyma or the renal pelvis. "To further clarify the expression of LINC02609 and SNHG17, we examined their expression in different renal cell lines and found that LINC02609 and SNHG17 were indeed significantly elevated in renal cancer cell lines." (PMID 40491925, 2025). "Previous studies have found that SNHG17 expression is significantly elevated in renal cancer, and its high expression is significantly correlated with tumor OS and different clinical features." (PMID 40491925, 2025). "A diagnostic model integrating those 5 FR-DELs (DOCK8-AS1, SNHG17, RUSC1-AS1, LINC02609, and LUCAT1) was established to separate patients with renal cancer from the normal group by using a stepwise logistic regression method." (PMID 35118117, 2021). "In the present study, we found that the expressions of SNHG17, RUSC1-AS1, LINC02609, and LUCAT1 were significantly increased while the expression of DOCK8-AS1 was significantly decreased in the patients with renal cancer and in renal cancer patients with high-risk values." (PMID 35118117, 2021). "Particularly, we found that the distribution of renal cancer patients with low-risk values was relatively concentrated, which could be well distinguished from renal cancer patients with high-risk values by using those 5 FR-DELs (DOCK8-AS1, SNHG17, RUSC1-AS1, LINC02609, and LUCAT1)." (PMID 35118117, 2021). "The patients with renal cancer with lower expression of DOCK8-AS1 displayed worse OS, and the patients with renal cancer with higher expressions of SNHG17, RUSC1-AS1, LINC02609, and LUCAT1 displayed worse OS." (PMID 35118117, 2021). "The expression of DOCK8-AS1 was significantly decreased, while the expressions of SNHG17, RUSC1-AS1, LINC02609, and LUCAT1 were increased significantly in patients with renal cancer." (PMID 35118117, 2021). "In the present study, we identified 5 FR-DELs (DOCK8-AS1, SNHG17, RUSC1-AS1, LINC02609, and LUCAT1) that could be used as biomarkers to predict the outcome of renal cancer." (PMID 35118117, 2021). "Finally, we identified 5 FR-DELs (DOCK8-AS1, SNHG17, RUSC1-AS1, LINC02609, and LUCAT1) correlated with the OS of renal cancer patients independently through a series of bioinformatics analyses." (PMID 35118117, 2021).
renal cell carcinoma (2 papers, 2022 to 2023). "Specifically, SNHG17 upregulates PAX6 to facilitate the development of oral squamous cell carcinoma, stimulates SOX4 to promote the epithelial-mesenchymal transition in ESCC cells, and activates H2AX-associated signaling pathways to promote the development of renal cell carcinoma." (PMID 37231440, 2023).
colorectal tumors (1 paper, 2025). "Together, these findings highlight PABPC1L, SNHG17 and SNHG1 as the most promising candidate biomarkers for distinguishing colorectal tumors from adjacent non-tumor tissues, with PABPC1L showing the most favorable balance of sensitivity and specificity." (PMID 41357316, 2025).
diabetic nephropathy (1 paper, 2022). "In non-tumor diseases, SNHG17 reduces MST ubiquitination and degradation and regulates the apoptosis of podocytes and Parkin-dependent mitophagy in diabetic nephropathy." (PMID 36185210, 2022).
diffuse large B-cell lymphoma (1 paper, 2023). "The results showed that the expression of SNHG17 in diffuse large B-cell lymphoma patients’ tissues was higher than that in normal control tissues (P < 0.001).To verify the expression of SNHG17 in lymphocytes, qPCR was used to detect the expression of SNHG17 in PBMC and various lymphoma cell lines." (PMID 37988356, 2023).
head and neck squamous cell carcinoma (1 paper, 2024). A squamous cell carcinoma that arises from any of the following anatomic sites: lip and oral cavity, nasal cavity, paranasal sinuses, pharynx, larynx, and salivary glands. "Research has shown that SNHG17 is intimately connected to the growth, invasion, migration, resistance to chemicals, and apoptosis of tumor cells, and head and neck squamous cell carcinoma patients whose SNHG17 expression was high had a significantly unfavorable prognosis." (PMID 38822402, 2024).
lung fibrosis (1 paper, 2023). "Altogether, these data reveal that modulation of radiation-induced EMT and lung fibrosis by treatment with LGG associates with a decrease in SNHG17 expression and the inhibition of SNHG17/PTBP1/Nothch1 axis." (PMID 36635762, 2023). "Mice of RIPF treated with LGG decreased SNHG17 expression and attenuated lung fibrosis." (PMID 36635762, 2023). "Mechanistically, SNHG17 can stabilize PTBP1 expression through binding to its 3′UTR, whereas the activated PTBP1 can bind with the NICD part of Notch1 to upregulate Notch1 expression and aggravated EMT and lung fibrosis post radiation." (PMID 36635762, 2023).
lymphoma (1 paper, 2023). A malignant (clonal) proliferation of B- lymphocytes or T- lymphocytes which involves the lymph nodes, bone marrow and/or extranodal sites. "Therefore, SNHG17 regulates the proliferation, apoptosis, and drug sensitivity of lymphoma cells by interacting with miR-34a-5p/EZH2." (PMID 37988356, 2023). "SNHG17 knockdown inhibited EZH2 expression, while miR-34a-5p overexpression weakened this trend, suggesting that the SNHG17/miR-34a-5p axis may affect the biological function of lymphoid cancer cells and tumor development by regulating the activity of the EZH2 signaling pathway." (PMID 37988356, 2023). "However, as an oncogene involved in tumor progression, the mechanism by which SNHG17 is involved in lymphoma progression remains unclear." (PMID 37988356, 2023).
Obesity (1 paper, 2024). Accumulation of substantial excess body fat. "Similarly, AA regulates the expression of SNHG17 and MIR100HG, known to be deregulated in various human cancers and in obesity, while DHA specifically up-regulates LIPE-AS1, a regulator of adipogenesis in animal models." (PMID 38542331, 2024).
pancreatic cancer (1 paper, 2023). "Moreover, a series of in vivo and in vitro experiments were conducted to assess the functions of SNHG17 from TAMs in the polarization and glycolysis of M2-like macrophages and in the proliferation and metastasis of pancreatic cancer cells (PCs)." (PMID 38098044, 2023).
cancer (32 papers, 2020 to 2025). A tumor composed of atypical neoplastic, often pleomorphic cells that invade other tissues. "SNHG17 is upregulated in various tumors and is closely associated with adverse prognosis and advanced clinical-pathological characteristics in cancer patients." (PMID 38439898, 2024). "As previous research studies have found SNHG17 is an oncogenic lncRNA and participant in multiple cancer regulation-associated signaling pathway, we focused on exploration its function from LGG modulation perspective." (PMID 36635762, 2023). "The paper also focuses on its different functions in various subcellular localizations and finally discusses the potential of SNHG17 as a new prognostic and diagnostic biomarker for cancer." (PMID 36185210, 2022). "Moreover, SNHG17 has been implicated in conferring resistance to chemotherapy and targeted therapies in specific cancers." (PMID 38098044, 2023). "SNHG17 is associated with increased cell proliferation capacity in various types of cancers." (PMID 36185210, 2022). "Previous studies have found that the expression of SNHG17 is up-regulated in ovarian, gastric, lung, prostate and other cancers." (PMID 40491925, 2025). "As a ceRNA, SNHG17 interacts with specific miRNAs (microRNAs) to modulate their target genes and, subsequently, influence key signaling pathways involved in cancer progression." (PMID 37755396, 2023). "Knockdown SNHG17 by siRNA inhibited A549 cancer cells’ migration ability whereas overexpression SNHG17 expression enhanced cell migration post radiation." (PMID 36635762, 2023). "They found SNHG17 is highly overexpression in colorectal cancer, promoted cancer cell proliferation and is an unfavorable prognostic factor." (PMID 36635762, 2023). "A recent review summarized SNHG17 is a novel cancer-related lncRNA which is highly overexpression in various cancers exerting oncogenic functions." (PMID 36635762, 2023). "SNHG17 has high expression in many cancer tissues and can be induced by many factors including m6A methyltransferase METTL3." (PMID 36635762, 2023). "Several studies previously assessed levels of SNHG17 in human HCCs and adjacent normal tissues via qRT-PCR and found a significant upregulation of SNHG17 in cancer tissues." (PMID 35248073, 2022). "Functionally, SNHG17 knockdown dampened the proliferative and invasive abilities of cancer cells via partial downregulation of FOXA1." (PMID 35248073, 2022). "SNHG17 overexpression was revealed to stimulate cancer progression by affecting cell growth and other cell behaviors." (PMID 34249085, 2021). "Small nucleolar RNA host gene 17 (SNHG17) is a conserved lncRNA that exerts crucial roles in regulating cancer progression." (PMID 34249085, 2021). "SNHG17 was also confirmed to be upregulated across cancers in the TCGA database, with the highest expression in CRC." (PMID 34782005, 2021). "The expression of SNHG17 was further examined in cell lines of different cancers from the Cancer Cell Line Encyclopedia (CCLE) database." (PMID 34782005, 2021). "Of them, SNHG17 has been reported to be aberrantly overexpressed in multiple human cancers, suggesting that SNHG17 has extensive functions and universal roles in tumorigenesis." (PMID 34782005, 2021). "Aberrant expression of SNHG17 has been reported to play oncogenic role in several cancers by regulating cancer cell proliferation, migration and metastasis." (PMID 32042267, 2020). "More studies are needed to further clarify the location and functions of SNHG17 in other types of cancers." (PMID 32351538, 2020). "Small nucleolar RNA host gene 17 (SNHG17), a novel cancer-related long noncoding RNA (lncRNA), was reported to be responsible for processing and developing in several cancers." (PMID 32042267, 2020). "STAT3, an important cancer-promoting transcription factor, was identified to activate SNHG17 transcription in OC." (PMID 32911343, 2020).
cancer (continued). "Small nucleolar RNA host gene 17 (SNHG17) belongs to lncRNA family, which has been elucidated in human cancers due to its oncogenic potential." (PMID 33292246, 2020). "Small nucleolar RNA host gene 17 (SNHG17) has emerged as an oncogene with upregulated expression in various tumors, such as colorectal and ovarian cancers, promoting tumorigenesis and protecting cancer cells from programmed cell death." (PMID 39897488, 2025). "This work revealed multiple functions of SNHG17, implicating it in several cancer hallmarks, including enhanced proliferation, the invasion of neighboring tissues, the stimulation of angiogenesis, the migration and formation of metastases, and interference with the apoptosis pathway." (PMID 37755396, 2023). "Concurrently, several studies were published that investigated the role of SNHG17 in cancer." (PMID 37755396, 2023). "Small nucleolar RNA host gene 17 (SNHG17) is a novel cancer-related lncRNA of the SNHG family which is highly expressed in various tumors and may exert oncogenic functions." (PMID 35248073, 2022). "The role of SNHG17 in DNA repair makes it a potential biomarker for cancer diagnosis and treatment." (PMID 36185210, 2022). "Expression and clinical significance of SNHG17 in human cancers." (PMID 36185210, 2022). "SNHG17 has been found to be involved in forming cancer hallmarks in numerous ways." (PMID 36185210, 2022). "In conclusion, we identify a SNHG17/LRPPRC/c-Myc regulatory axis and characterize its function in G1/S transition, which uncovers new mechanisms underlying cell proliferation and tumor growth, and provides potential targets for anti-cancer therapy." (PMID 34671012, 2021). "All these data suggest that SNHG17 is a pan-cancer oncogene and may be a promising therapeutic target across cancers." (PMID 34782005, 2021). "Recent studies have indicated the oncogenic role of SNHG17 in several cancer types, including CRC." (PMID 34782005, 2021). "Previous investigations have shown that SNHG17 could exert as a biological participant in different types of human cancers." (PMID 33292246, 2020). "Similarly, SNHG17, which is overexpressed in different cancer tissues, likely through amplifications, promotes cancer cell proliferation and constitutes a marker of poor prognosis." (PMID 33329688, 2020). "Furthermore, SNHG17 expression levels were positively correlated with cancer process stage." (PMID 36635762, 2023). "Therefore, SNHG17 is an emerging biomarker for cancer diagnosis and prognosis." (PMID 36185210, 2022). "However, miR-124-3p could regulate multiple targets genes, we would investigate whether SNHG17 could modulate these target genes in BC to further explore molecular mechanism of SNHG17 in this cancer." (PMID 32042267, 2020). "Previous studies have found that SNHG17 has a significant increase in KIRC and can promote cancer progression." (PMID 40491925, 2025). "As of the reported oncogenic property of SNHG17, we further validated that SHNG17 expression increased in A549 and H1299 cancer cells compared with normal lung epithelial cell, HBE and BEAS2B cells." (PMID 36635762, 2023). "SNHG17 was initially confirmed to be highly expressed in CRC, and then its overexpression was observed in a variety of cancers." (PMID 34782005, 2021). "Previous studies have demonstrated that the expressions of SNHG17, RUSC1-AS1, LINC02609, and LUCAT1 were significantly increased in many cancers." (PMID 35118117, 2021). "No other clinicopathologic or demographic variable, including sex, BMI group, tumor location, TNM stage, chronic disease status, or family history of cancer, showed a significant relationship with the expression of RUSC1-AS1, SNHG17, PABPC1L, or SNHG1 (all p > 0.05)." (PMID 41357316, 2025). "Small nucleolar RNA host gene 17 (SNHG17) is a newly discovered tumour‐related lncRNA of the SNHG family which is highly expressed and may exert cancer‐promoting effects in multiple cancers." (PMID 38680032, 2024).
cancer (continued). "By interacting with miR-23a-3p/23b-3p/23c, SNHG17 upregulates the expression of UBE2M and OTUB1, which have been demonstrated to play critical roles in the tumorigenesis of human cancers, more importantly promoting cancer cell immunosuppression and resistance to cytotoxic stimulation." (PMID 35864871, 2022). "Besides, we validated that SNHG17 positively regulated SNORA71B in all PC cell lines we applied and also in other cancer cell lines in which SNHG17 was identified as an oncogene." (PMID 32447342, 2020). "However, up until now, it is still unkwon whether SNHG17 and LINC00837 involve in regulating cancer progression via affecting lipid metabolism, which makes investigations on this issue especially important and necessary." (PMID 37231440, 2023).